DCAF13 (DDB1 and CUL4 associated factor 13)
Diseases named in the same sentence as DCAF13 in open-access papers (continued):
Sharing a sentence is not in itself a finding about the gene and the disease.
tumor (16 papers, 2017 to 2025). "Together, these findings broaden our understanding of the functions and mechanisms of DCAF13 in tumors and provide a stronger theoretical basis for considering DCAF13 as a potential target for tumor therapy." (PMID 38163876, 2024). "Tumor formation assays in mice revealed that tumor size and weight were significantly reduced in the DCAF13 knockdown group compared to the control group." (PMID 38163876, 2024). "Previous studies have shown that DCAF13 is involved in promoting tumor growth via the induction of protein or mRNA degradation." (PMID 38163876, 2024). "Only a single up-regulated gene, DCAF13 (DDB1 and CUL4 associated factor 13) (boxed in orange) was found to be correlated with the only up-regulated tumor capsule specific lncRNA, DCAF13P3 (boxed in orange)." (PMID 32636408, 2020). "Furthermore, nivolumab (NIVO) can also protect tumor cells from treatment by upregulating several genes, including DCAF13." (PMID 37827692, 2023). "We then assumed that USP2-AS1 might promote DCAF13 by targeting these putative tumor-suppressive substrates, especially ATR." (PMID 36359803, 2022). "All these findings suggested that USP2-AS1 might regulate DCAF13 by targeting these tumor suppressors." (PMID 36359803, 2022). "For several examples above, like SOF1/DCAF13, genes could be targeted as both a driver of the tumor and as a sensitizer to doxorubicin." (PMID 31660150, 2019). "The overexpression of DCAF13, EZR, and MRPL13 in patients were associated with lower survival, which reveals that these genes might be associated with tumor invasion, progression and poor prognosis." (PMID 30881302, 2019). "Both heterozygous and homozygous CNV analyses showed significant amplification for DCAF13 and FAM83D and deletion for FUCA2, UQCRH, and NDC80 in tumor samples." (PMID 41355397, 2025). "PRDX6, MAGOHB, NUCKS1, DCAF13, and TXN displayed opposite trends on their potential facilitation of CTL function as well as correlations with immune checkpoints and TILs (tumor-infiltrating lymphocytes) compared to ITGAL, ITGAX, and TMEM119 in NSCLC." (PMID 37835514, 2023). "Similarly, DCAF13 and PPM1G have been shown to promote HCC progression by degrading tumor suppressors or modulating oncogenic signaling." (PMID 41355397, 2025). "Given that morphological plasticity is a key determinant of cell migration, many of the identified genes were found to have a role in promotion of tumor cell migration and invasion, including ECM production and mesenchymal state induction (HEG1, BZW2, DCAF13, SQLE, PKIA)." (PMID 35879361, 2023). "The top 100 genes that correlated with NUDCD1 expression indicated 4 common members: FAM91A1, DCAF13, MED30 and DDX21, and their corresponding expression in different tumor types could be established." (PMID 37338527, 2023). "BAG2 might favor cell proliferation, repress apoptosis and facilitate tumor invasion in HCC, probably through regulation on ribosome biogenesis via genes like WDR12, BYSL, and DCAF13." (PMID 34257542, 2021). "For instance, the human homologous genes for the murine genes upregulated by taxifolin in LL2 tumors, including Prdx6, Magohb, Nucks1, Dcaf13, and Txn1, acted to facilitate the CTL-mediated killing of tumor cells, as shown by their negative T cell dysfunction values." (PMID 37835514, 2023).
cancer (9 papers, 2019 to 2025). A tumor composed of atypical neoplastic, often pleomorphic cells that invade other tissues. "DCAF13 was strongly correlated with SLC25A32 in most cancers (R = 0.75), followed by FAM91A1 (R = 0.69) and TAF2 (R = 0.68)." (PMID 39624160, 2024). "DDB1 and CUL4 associated factor 13 (DCAF13) is a substrate receptor in the CUL4‐DDB1 E3 ligase, and its expression is associated with the prognosis of certain cancers." (PMID 34775691, 2022). "On the other hand, it increases the probability of metastasis of drug‐resistant cancer cells by increasing DCAF13 expression." (PMID 34775691, 2022). "Furthermore, DCAF13 expression was positively correlated with advanced pathologic stages, indicating its correlation with cancer progression." (PMID 34775691, 2022). "A few studies also suggest that DCAF13 is an important player in cancers." (PMID 34775691, 2022). "DCAF13 has been shown to be involved in some biological processes and a few types of human cancer." (PMID 34775691, 2022). "In addition to the essential functions of DCAF13 during mammalian oocyte and embryonic development, overexpression of DCAF13 is linked to poorer outcomes for patients with several different types of cancers, suggesting that DCAF13 may serve as an oncogene." (PMID 36217444, 2022). "Consistent with this notion, the mouse homologous genes of human PRDX6, MAGOHB, NUCKS1, DCAF13, and TXN were upregulated by taxifolin in LL2 LC tumors and facilitated CTL-derived toxicity towards cancer cells." (PMID 37835514, 2023). "Furthermore, our findings suggest that high DCAF13 expression is a poor prognostic indicator in LUAD, and DCAF13 may be a potential therapeutic target for treating with this aggressive cancer." (PMID 38163876, 2024). "In this regard, PRDX6, MAGOHB, NUCKS1, DCAF13, and TXN displayed an overall negative correlation with multiple immune checkpoints in LUAD, LUSC, and other cancer types." (PMID 37835514, 2023).
DCAF13 also shares sentences with these, for which no sentence is quoted: osteosarcoma (2 papers); lymphoma (1); mantle cell lymphoma (1); migraine (1); non-small cell lung carcinoma (1).